DDB2 (damage specific DNA binding protein 2)
Diseases named in the same sentence as DDB2 in open-access papers (continued):
Sharing a sentence is not in itself a finding about the gene and the disease.
melanoma (14 papers, 2013 to 2025). A malignant, usually aggressive tumor composed of atypical, neoplastic melanocytes. "To date, somatic mutations in XPC, DDB1 and DDB2 have rarely been reported in melanoma tumours." (PMID 29373959, 2018). "More importantly, the DDB2 mRNA levels were substantially lower in samples derived from metastatic tissue than that of samples originated from premetastatic tissue in the TCGA-melanoma cohort." (PMID 37142578, 2023). "Expression of the DNA damage recognition GGR components XPC, DDB1 and DDB2 was significantly higher in melanocytes than melanoma from 4 or 8 to 48 hours after UVB irradiation." (PMID 27487145, 2016). "The transcript levels of XPC, DDB1 and DDB2 were also quantified in melanoma tumours and compared to clinical information." (PMID 27487145, 2016). "Despite this, melanoma cells displayed a DDB2 protein induction profile comparable to melanocytes, and two (Sk-Mel-28, Mel-RM) of four melanoma cell lines displayed induction of DDB1 similar to normal melanocytes." (PMID 26913219, 2015). "We recently reported only a limited induction of XPC, DDB1 and DDB2 GGR transcripts in melanoma cell lines 24 hours after cisplatin treatment suggesting a breakdown in the normal NER response to DNA damage." (PMID 23940574, 2013). "We found that several HRR-associated genes, including DDB2, RAD51, BRCA1, XRCC2 and BRCA2, are overexpressed in melanoma cells compared to primary melanocyte cultures, while the expression of the NER-associated genes XPA, ERCC1 and ERCC4 showed no clear differences." (PMID 32719412, 2020). "Furthermore, a correlation between low DDB2 expression level and poor outcomes was established among patients with melanoma, colon, ovarian, lung, breast, brain or head, and neck cancers, suggesting a critical role for DDB2 in tumor suppression." (PMID 31635251, 2019). "Expression of GGR components XPC, DDB1 and DDB2 was significantly lower in melanoma after UVB." (PMID 27487145, 2016). "Therefore, attenuation of GGR components XPC and DDB2 would also confer an anti-apoptotic phenotype in addition to the accumulation of DNA damage, both of which are key features of melanoma." (PMID 27487145, 2016). "Interestingly, at baseline XPC and DDB2 were expressed at similar levels in melanocyte and melanoma cell lines." (PMID 27487145, 2016). "Moreover, we confirmed that SIRT6 interacted with DDB2 in the melanoma cell line A875." (PMID 32789493, 2020). "Subdividing the whole TCGA-SKCM cohort by median age, we found that in melanoma tissue from younger patients, XP cluster 1 genes and also XPC and DDB2, belonging to XP cluster 2, were expressed to a relatively higher extent." (PMID 35174087, 2022). "We have shown an overexpression of RAD51 and other HRR genes, DDB2, XRCC2, BRCA1 and BRCA2, in melanoma cell lines and this has a protective role against DNA damage accumulation after genotoxic stress." (PMID 32719412, 2020). "Given the significantly lower DDB1 and DDB2 transcript expression observed in melanoma cells, this suggests enhanced translation rate or protein stability of DDB1 and DDB2 in melanoma cells." (PMID 26913219, 2015). "We have found that the three GGR components XPC, DDB1 and DDB2 do not respond to UV treatment in melanoma cell lines, resulting in reduced repair of UV-induced DNA damage." (PMID 29373959, 2018). "Standard chemotherapeutics, such as cisplatin, are ineffective on metastatic melanoma and we, and others, have shown that levels of a number of NER proteins in melanoma cells are elevated in response to cisplatin: ERCC1 and XPF, XPC and DDB2, XPA (this publication)." (PMID 29254481, 2017). "Expression of GGR components, XPC, DDB1 and DDB2 significantly increased in response to cisplatin in melanocytes but this increase was noticeably absent in melanoma." (PMID 27487145, 2016).
melanoma (continued). "Importantly, DNA repair transcripts PCNA and BRCA1, both of which have previously been reported to regulate DDB1 and DDB2 transcript expression, had significantly higher induction in melanocytes 24 hours after cisplatin treatment but not in the majority of the melanoma cell lines." (PMID 23940574, 2013). "In this first study to investigate NER in melanoma after UVB we have confirmed that GGR is reduced in melanoma by showing delayed repair of both 6-4 PPs and CPDs, particularly in the crucial S-phase of the cell cycle, and lack of induction of XPC, DDB1 and DDB2 after UVB." (PMID 27487145, 2016).
skin cancer (12 papers, 2012 to 2023). "In animal models, Ddb2-deficient mice are also predisposed to UV-induced skin cancer and several other types of cancers." (PMID 32722430, 2020). "DNA damage-binding protein 2 (DDB2) has been considered a tumor suppressor based on the findings that DDB2-knockout mice were not only susceptible to UV-induced skin cancer, but also more vulnerable to spontaneous malignant neoplasms." (PMID 29752431, 2018). "Accordingly, all five specific skin cancer genes from the NER class - DDB2, ERCC3, ERCC5, XPA, and XPC - are associated with UV-sensitive skin." (PMID 26856619, 2016). "Consistent with the phenotype of XP patients, DDB2−/− mice are predisposed to UV induced skin carcinoma formation." (PMID 23109835, 2012). "Evidence has shown that DDB2 is downregulated in skin cancer, and the DDB2 knockout mice exhibited much higher incidence in developing UV-induced skin cancer." (PMID 32090112, 2020). "The Ddb2 knock out mice are tumor prone and in response to UV-damage or on exposure to mutagens produce skin cancer and colon adenocarcinomas." (PMID 30410671, 2018). "Xeroderma Pigmentosum patients harbouring defects in XPC and DDB2 genes are more prone to develop ocular surface (including the cornea) and skin cancers, demonstrating the importance of DNA repair in cancer prevention of corneal cancer." (PMID 27611318, 2016). "Therefore, the Xeroderma pigmentosum patients deficient in DDB2, XPC, and XPA genes are highly cancer prone and display over 2,000-fold increased incidence rates of skin cancer due to defects in NER pathway." (PMID 27442013, 2016). "However, recent studies from our group suggests that DDB2 mediated premature senescence response also serves an important part in its role as an inhibitor of UV induced skin carcinoma formation." (PMID 23109835, 2012). "Therefore, quite intriguingly, in the context of UV induced skin carcinoma progression, DDB2 and p21 Waf1/Cip1 cooperate with each other to inhibit tumorigenesis by induction of premature senescence." (PMID 23109835, 2012). "It is also noteworthy in this regard that mouse models lacking XPC and/or DDB2 are prone to tumors in internal organs in addition to being sensitive to UV-induced skin tumors." (PMID 33937266, 2021).
colorectal cancer (6 papers, 2007 to 2025). A primary or metastatic malignant neoplasm that affects the colon or rectum. "The association between downregulated DDB2 expression and poor patient survival is also observed in colorectal cancer, astrocytoma, and another HNC cohort." (PMID 32722430, 2020). "For example, upregulated DDB2 expression was detected in colorectal cancer tissues." (PMID 39335143, 2024). "As examples of genetic polymorphisms that affect onset age of cancers other than that examined in this study, some reports discuss MMP-1 and DDB2 in lung cancer, and CCND1 in HNSCC and colorectal cancer." (PMID 17919326, 2007).
gastric cancer (6 papers, 2017 to 2025). A primary or metastatic malignant neoplasm involving the stomach. "Previous studies showed that polymorphisms in the DDB2 gene may contribute to the etiology of lung cancer, gastric cancer, and head and neck cancer." (PMID 32090112, 2020). "Conversely, DDB2 knockdown has been shown to enhance cell proliferation in gastric cancer." (PMID 41208896, 2025). "Inversely, DDB2 has been shown to promote the migration of gastric cancer cells." (PMID 36568213, 2022). "In addition, DDB2 interacts with PAQR3 to modulate the tumorigenesis of gastric cancer." (PMID 33955706, 2021).
head and neck squamous cell carcinoma (6 papers, 2007 to 2025). A squamous cell carcinoma that arises from any of the following anatomic sites: lip and oral cavity, nasal cavity, paranasal sinuses, pharynx, larynx, and salivary glands. "In addition, DDB2 has been shown to repress epithelial-to-mesenchymal transition (EMT) in colon cancer and in oral/head and neck squamous cell carcinoma (HNSCC)." (PMID 39333096, 2024).
prostate carcinoma (6 papers, 2017 to 2024). A carcinoma that arises from epithelial cells of the prostate gland. "In clinical significance, NRIP was a candidate tumor promoter and DDB2 was a tumor suppressor in prostate cancer." (PMID 28212551, 2017). "Accordingly, DDB2 expression may be induced in prostate cancer tissues with high levels of AR expression." (PMID 28212551, 2017). "Here, we demonstrated that DDB2 expression is reduced in human prostate cancer." (PMID 28212551, 2017). "Because DDB2 reportedly promotes the ubiquitination and degradation of AR in LNCaP cell lines, we next examined the relationship between DDB2 and AR protein expression in human prostate cancer tissues." (PMID 28212551, 2017). "Collectively, DDB2 expression is down-regulated in human prostate cancer." (PMID 28212551, 2017). "Consistently, our data support that DDB2 functions as a tumor suppressor in prostate cancers." (PMID 28212551, 2017). "As the DDB2 expression level is found to be lower in prostate cancer tissues compared to non-neoplastic ones, this could interfere with AR homeostasis and induce subsequent AR-dependent prostate cancer growth." (PMID 31635251, 2019). "The relationship between DDB2 and prostate cancer remains unclear." (PMID 28212551, 2017). "Therefore, the correlation of AR and DBB2 expression in prostate cancers seems logical, because high levels of AR expression in cancer cells may activate the DNA repair mechanism that up-regulates DDB2 expression." (PMID 28212551, 2017). "Therefore, we were interested in examining the NRIP, DDB2 and AR protein expression profiles in human prostate tumors with the aim of elucidating the interaction mechanism of these three proteins and their roles in prostate cancer." (PMID 28212551, 2017). "First, the expression profiles of five key radiation-responsive genes (FDXR, SESN1, GADD45, DDB2, and MDM2) during the course of RT in the blood of 8 prostate cancer patients treated with IMRT and SABR were analyzed." (PMID 32519025, 2020). "In summary, we propose that NRIP and DDB2, through competitive binding to the AR, antagonize each other's function in maintaining AR homeostasis and disruption of the balance between these two proteins may contribute to the pathogenesis of a specific type of aggressive prostate cancer." (PMID 28212551, 2017). "In the prostate cancer cell line LNCaP, NRIP displaced DDB2 to prevent DDB2 degrading the AR in the CUL4-DDB2-E3 ligase complex." (PMID 28212551, 2017). "The relationship between the expression of NRIP, AR and DDB2 and the pathological sub-types of prostate cancer, we found that a specific pattern of high expression of NRIP and AR and simultaneous low expression of DDB2 was detected more frequently in cribriform tumors than in non-cribriform tumors." (PMID 28212551, 2017). "Collectively, the specific expression pattern of NRIP, AR and DDB2 in the cribriform type of human prostate cancer is consistent with our hypothesis that NRIP protects against AR degradation by DDB2 in the CUL4-DDB1 E3 ligase complex, in at least a subset of prostate cancers." (PMID 28212551, 2017). "Initially we noticed that ∼ one fifths of our prostate cancer samples were cribriform tumors; we then analyzed the expression patterns of NRIP, AR, and DDB2 in the context of the prostate cancers with or without the cribriform pattern." (PMID 28212551, 2017).
breast tumor (5 papers, 2008 to 2021). "Involvement of ER and other transcription factors or other molecular mechanisms are not excluded and future investigations will need to elucidate the regulation of DDB2 expression during breast tumor progression." (PMID 18431487, 2008). "In addition, overexpression of DDB2 reduces the migration and invasion of metastatic breast tumor cells by attenuating the activity of NF-κB60." (PMID 30923324, 2019). "In addition, a correlation between DDB2 expression and ER status was observed also in breast tumor samples from patients." (PMID 18431487, 2008).
lung carcinoma (5 papers, 2007 to 2025). "In this study, elevated DDB2 levels found in breast, liver, cholangiocarcinoma, and lung cancers correlated with reduced patient survival." (PMID 41208896, 2025). "Our study identifies DDB2 as a critical regulator of DNA repair-driven chemoresistance in breast, liver, cholangiocarcinoma, and lung cancers." (PMID 41208896, 2025). "Moreover, our previous study has shown deregulation of the genes encoding the NER-related molecular components of the heterodimer DDB complex (DDB1 and DDB2) in patients with lung cancer." (PMID 39766117, 2024). "Given that both DDB2 and XPC are key components of NER machinery, we sought to determine whether the NER pathway is involved in KRAS mutation–driven platinum resistance in lung cancer." (PMID 39960727, 2025). "In addition, the m6A methylation levels of DDB2 and XPC transcripts were also higher in primary KRAS-mutant lung cancer cells compared with primary KRAS WT lung cancer cells." (PMID 39960727, 2025). "Moreover, qRT-PCR analyses showed that both the DDB2 and XPC genes were expressed at much higher levels in primary KRAS-mutant lung cancer cells compared with primary KRAS WT lung cancer cells." (PMID 39960727, 2025).
acne (4 papers, 2020 to 2022). An inflammatory process of the sebaceous glands which is characterized by comedones, nodules, papules and/or pustules on the skin. "They identified two new susceptibility loci at 11p11.2 [DDB2 (damage-specific DNA-binding protein 2)] and 1q24.2 [SELL (L-selectin)], which are involved in androgen metabolism, inflammation processes and scar formation in severe acne." (PMID 36439142, 2022).
colon adenocarcinoma (4 papers, 2018 to 2025). "Previous studies have demonstrated that DDB2 is a potent regulator of EMT in colon adenocarcinoma and in HNSCC." (PMID 36568213, 2022). "Our previous studies show that DDB2 is involved in the regulation of metastasis in colon adenocarcinoma." (PMID 30410671, 2018). "In a previous study, we reported similar role of DDB2 in regulating EMT-TFs in colon adenocarcinoma cells." (PMID 30410671, 2018). "Recent studies from our lab revealed that DDB2 is a potent regulator of EMT and metastasis in colon adenocarcinoma cells, the mechanism indicated the transcription regulatory function of DDB2 in repressing expression of pro-EMT transcription factors (EMT-Tfs), SNAIL and ZEB1." (PMID 30410671, 2018). "Furthermore, the epigenetic regulation patterns of the HIF1A promoter by DDB2 and Suv39h1 via histone-marked H3K9Me3 were similar to the constitutive repression of DDB2-mediated EMT-related regulators in colon adenocarcinoma cells." (PMID 36190612, 2022).
Fanconi anemia (3 papers, 2022 to 2025). Fanconi anemia (FA) is a hereditary DNA repair disorder characterized by progressive pancytopenia with bone marrow failure, variable congenital malformations and predisposition to develop hematological or solid tumors. "TONSL knockdown significantly reduced the expression of FANCD1 and XRCC2, both key players in the Fanconi anemia and homologous recombination repair pathways, while DDB2 and NEIL3 showed no statistically changes." (PMID 39944694, 2025).
xeroderma pigmentosum group E (3 papers, 2008 to 2023). "Mutations in the DDB2 gene leading to its loss of function are responsible for the phenotypic features of xeroderma pigmentosum group E (XP-E) patients, characterized by malignant skin tumors." (PMID 18431487, 2008).
astrocytoma (2 papers, 2020 to 2022). "The genes CDH2, DDB2, DSP, EPO, FGF2, and TEK were overexpressed in an astrocytoma cell line." (PMID 36142793, 2022).
basal cell carcinoma (2 papers, 2012 to 2021). A carcinoma involving the basal cells. "It has been validated at the protein level as well in basal cell carcinoma patient samples where there is evidence for loss of DDB2 expression compared to the normal tissue." (PMID 23109835, 2012).
cervical cancer (2 papers, 2021). A primary or metastatic malignant neoplasm involving the cervix. "Various genes, namely GLS, CD36, WNT5a, HRAS, DDB2, PIK3R2, and CDH2 were found to be differentially highly expressed in primary cervical cancer samples of patients who developed distant recurrence." (PMID 35087740, 2021). "Namely, GLS, CD36, WNT5a, HRAS, DDB2, PIK3R2, and CDH2 were significantly DE between cervical cancer without recurrence and cervical cancer with distant recurrence." (PMID 35087740, 2021).
Cockayne syndrome (2 papers, 2015 to 2024). A multisystem condition characterized by short stature, a characteristic facial appearance, premature aging, photosensitivity, progressive neurological dysfunction, and intellectual deficit. "TCR‐NER requires Cockayne syndrome group A and Cockayne syndrome group B to detect the lesion, while in GGR‐NER, the XPC and DNA damage‐binding protein B2 (DDB2) participate in the process." (PMID 39492835, 2024). "This is directly attributable to causative disease mutations being present in GGR genes, XPC and DDB2 (XPE) in patients with XP, but not in the transcription coupled repair (TCR) genes CSA and CSB in Cockayne’s syndrome." (PMID 26913219, 2015).
glioblastoma (2 papers, 2017 to 2025). The most malignant astrocytic tumor (WHO grade IV). "A total of 5 key DNA repair genes, CDK7, DDB2, RNH1, RFC2 and FAH, were screened to be significantly related to the prognosis of glioblastomas (p = 9.74e−05)." (PMID 28938550, 2017).
liver cancer (2 papers, 2021 to 2025). An epithelial or non-epithelial malignant neoplasm that arises from the liver. "To figure out whether it is a common mechanism that CRL4DDB2 regulated CDT2 degradation in other cells, we silenced DDB2 in Chang liver cancer cells and human primary lung fibroblast CCC-HPF-1 cells." (PMID 33557942, 2021).